OR5H6 (olfactory receptor family 5 subfamily H member 6)
Description:
Odorant receptor.
Synonyms: OR3-11
Tractability: Antibody: UniProt places it where antibodies can reach, with medium confidence; UniProt predicts a signal peptide or a membrane-spanning region; its Gene Ontology location is reachable by antibodies, with medium confidence. PROTAC: ubiquitination databases record sites on it.
Gene: Protein-coding gene on chromosome 3 (98,263,252 to 98,265,356, forward strand). Ensembl gene ENSG00000230301.
Subcellular location: Cell membrane
Pathways (Reactome):
Sensory Perception: Expression and translocation of olfactory receptors
Gene Ontology:
Molecular function: odorant binding; olfactory receptor activity; G protein-coupled receptor activity
Biological process: sensory perception of smell; detection of chemical stimulus involved in sensory perception of smell; G protein-coupled receptor signaling pathway
Cellular component: plasma membrane; membrane
Genetic constraint (gnomAD): Loss-of-function variants: 0 observed, 0.0749 expected, observed/expected ratio (o/e) 0, 90% interval 0 to 1.89. That is too few expected variants to judge how well the gene tolerates losing a copy. Missense variants: 427 observed, 358.88 expected, observed/expected ratio (o/e) 1.19, 90% interval 1.1 to 1.29. Synonymous variants: 150 observed, 127.39 expected, observed/expected ratio (o/e) 1.18, 90% interval 1.03 to 1.35.
Homologues: Orthologues: chimpanzee OR5H6 (92% identical), dog OR5H13 (75% identical), mouse Or5h19 (75% identical), mouse Or5h26 (75% identical), rat Or5h26 (74% identical), rat Or5h26b (74% identical), dog OR5H11 (73% identical), dog OR5H9 (73% identical), mouse Or5h17 (72% identical), rat Or5h17 (72% identical), rat Or5h17b (72% identical), rat Or5h17c (72% identical), and 13 more. Paralogues in human: OR5H14 (86% identical), OR5H1 (82% identical), OR5H15 (81% identical), OR5H2 (78% identical), OR5H8 (65% identical), OR5AC2 (60% identical), OR5K1 (54% identical), OR5K2 (52% identical), OR5K4 (51% identical), OR5K3 (49% identical), OR5B21 (48% identical), OR8U1 (48% identical), and 84 more.